FOXE1 (forkhead box E1)
Diseases named in the same sentence as FOXE1 in open-access papers (continued):
Sharing a sentence is not in itself a finding about the gene and the disease.
thyroid (20 papers, 2009 to 2025). "Broadly, we found little evidence of association with serum TSH levels for SNPs, apart from FOXE1, that have been associated with other thyroid-related phenotypes." (PMID 25436638, 2014). "Moreover, as its role with the expression of TG and TPO suggests, mutations at the FOXE1 locus in 9q22 have been associated with thyroid disorders such as congenital HT due to thyroid dysgenesis, primary HT, goiters, nonmedullary thyroid cancer, PTC, and TC." (PMID 28928994, 2017). "The same effect was also observed for the FOXE1 rs1867277 polymorphism, suggesting that thyroid alterations may be influenced by the environment (nitrates in drinking water) and genetic factors (polymorphisms in the FOXE1 gene) and confirming the existence of gene-environment interactions." (PMID 40587020, 2025). "Generally, various genetic and molecular studies addressed the issue of congenital hypothyroidism (for example, anomalies of TSHR, SLC26A7, JAG1, DUOX2, and FOXE1 gene) linking the thyroid dyshormonogenesis to thyroid dysgenesis." (PMID 38791947, 2024). "The CH group with thyroid dysgenesis was largely and significantly enriched with the 14-Alanine-FOXE1 homozygosity." (PMID 37008944, 2023). "According to previous reports, the cause of CH in approximately 80%–85% of patients is thyroid dysgenesis (including agenesis, ectopy, and hypoplasia), which is related to gene mutations in TSHR, PAX8, TTF1/NKX2-1, and TTF2/FOXE1." (PMID 37252044, 2023). "Thyroid dysgenesis has been primarily associated with mutations in genes such as those encoding the TSH receptor (Tshr), Forkhead box protein E1 (Foxe1), and the Paired box protein Pax-8 (Pax8)." (PMID 34502288, 2021). "Emerging evidence suggests a potential molecular link between AT and thyroid malignancies, characterized by the co-expression of multiple genes such as TSHR, BTB domain and CNC homolog 2 (BACH2), and forkhead box E1 (FOXE1), along with shared somatic mutations." (PMID 41153734, 2025). "Here, we bring new evidence about the role of FOXE1 in thyroid pathogenesis." (PMID 37008944, 2023). "However, a previous GWAS of hypothyroidism observed that the Forkhead box protein E1 (FOXE1) risk allele identified is associated with several thyroid phenotypes, including thyroiditis, nodular and multinodular goiters, and thyrotoxicosis." (PMID 30248900, 2018). "Recently, the Foxe1 mutation is known to be associated with the molecular pathology of ectopic thyroid in mouse models; however, no known gene for human ectopic thyroid has been demonstrated." (PMID 26047938, 2015). "In an attempt to discern the role of FOXE1 in thyroid tumorigenesis, and considering that this gene is involved in the migration of thyroid cells from the pharyngeal floor to the trachea during development, we hypothesized that FOXE1 could be involved in thyroid tumor cell migration." (PMID 31846430, 2020). "This abnormal localization of FOXE1 could be related to thyroid tumorigenesis." (PMID 31846430, 2020). "The genes associated with thyroid morphogenesis such as NKX2-1, NKX2-5, PAX8, FOXE1, and thyroid-stimulating hormone receptor (TSHR) have been reported to be involved in thyroid dysgenesis." (PMID 32394050, 2020).
thyroid dysgenesis (17 papers, 2009 to 2025). "In support of the multifactorial nature of thyroid dysgenesis, polymorphisms in the polyalanine tract of the FOXE1 gene have been demonstrated to modulate the genetic susceptibility for thyroid dysgenesis." (PMID 41303336, 2025). "This is caused by mutations in the FOXE1 gene and is characterized by thyroid dysgenesis, cleft palate, spiky hair, and, in some cases, bifid epiglottis or choanal atresia." (PMID 41303336, 2025). "In the Chinese population, abnormal expression of FOXE1 was linked to CH-based thyroid dysgenesis (OMIM 218700)." (PMID 38919955, 2024). "FOXE1 mutations have been associated with phenotypes including congenital hypothyroidism and thyroid dysgenesis." (PMID 37435181, 2021). "They concluded that FOXE1 significantly modulates the risk of thyroid dysgenesis occurrence through its alanine-containing stretch and proposed a mechanism linking the polyalanine tract containing transcription factors to disease." (PMID 19626132, 2009). "In this study, we report for the first time that a novel heterozygous point mutation (p.Leu107Val) affecting FOXE1 DBD may be sufficient to cause thyroid dysgenesis and CH only when associated with homozygous Ala-14-FOXE1." (PMID 37008944, 2023). "Moreover, clinical studies on humans have shown that changes in the structure of FOXE1 gene (caused by mutations or alterations in the size of the polyA tract) are linked to TD, causing thyroid agenesis." (PMID 29479488, 2017). "Furthermore, mutations of the FOXE1 gene cause human syndromes that are associated with thyroid agenesis, among other phenotypes." (PMID 24489898, 2014). "Similarly, mutations in the forkhead DNA-binding domain of the human FOXE1 gene cause thyroid agenesis, cleft palate and choanal atresia similar to the phenotype observed in FOXE1-null mutant mice." (PMID 21999483, 2011). "The possible causes of thyroid dysgenesis include the impact of maternal antithyroid immunoglobulins, genetic mutations, and genes of transcription factors, such as TITF1/NKX2–1, PAX8, FOXE1, and HHEX." (PMID 34713843, 2021). "There have been no reported cases of isolated thyroid dysgenesis, and thus screening for FOXE1 mutation in patients with dysgenesis should be guided by the presence of associated features." (PMID 41303336, 2025). "Notably, eight mutations in four genes (FOXE1, NKX2-1, PAX8 and HHEX) that lead to thyroid dysgenesis were identified in eight probands." (PMID 29650690, 2018). "Cases of thyroid dysgenesis are usually sporadic, inherited genetic defects are only recognized in about 2% of all cases and result from transcription factor genes mutations (PAX8, NKX2-1/TITF1, NXK2-5, FOXE1/TITF-2)." (PMID 25908941, 2015).
hypothyroidism (14 papers, 2012 to 2024). Abnormally low levels of thyroid hormone. "SOX2 is highly correlated with FOXE1, whose congenital mutations cause cleft palate and hypothyroidism." (PMID 30704473, 2019). "While association with hypothyroidism has been established at the FOXE1 locus, the co-association of variants with myopia and clefting is a novel observation suggesting shared etiologies." (PMID 28087736, 2017). "FOXE1 rs1877432, previously associated with hypothyroidism, generalized to serum TSH levels in African Americans (p = 9.73×10−3, β = 0.11)." (PMID 25436638, 2014). "The FOXE1 gene has been previously associated with hypothyroidism and is known to regulate transcription of TPO." (PMID 24586183, 2014). "An additional SNP in FOXE1, rs965513, previously associated with hypothyroidism, generalized to serum TSH levels in European Americans (p = 1.09×10−6, β = −0.05)." (PMID 25436638, 2014). "FOXE1 has recently been associated with hypothyroidism (as well as several other thyroid conditions) in a GWAS with 1,317 hypothyroidism cases determined from medical records." (PMID 22493691, 2012). "FOXE1 is also involved in thyroid development and coding mutations cause congential hypothyroidism." (PMID 22493691, 2012). "Moreover, reports associating FOXE1 poly-Ala variations with low fT4 levels indicate that the Ala-14 allele may favor the onset of hypothyroidism in combination with other genetic, epigenetic and environmental factors, in the context of a complex origin of CH." (PMID 37008944, 2023). "Some of the hypothyroidism loci had already previously been implicated in hypothyroidism through GWAS, including TPO, FOXE1, VAV3, and a variant in ATXN2 (rs597808) in high linkage disequilibrium (LD) with the R262W polymorphism in SH2B318." (PMID 30367059, 2018). "VAV3 is involved in immune function, and FOXE1 and PTPN22 have previously been associated with hypothyroidism." (PMID 22493691, 2012). "Similarly, polymorphisms in the listed genes VAV3, SH2B3, FOXE1 and PTPN22 were identified in the 23andMe database to be associated not only with hypothyroidism but also with other autoimmune diseases." (PMID 38919955, 2024). "FOXE1 variants, associated with hypothyroidism, were not genome-wide significant (rs10759944: p = 1.08×10−6, β = −0.05)." (PMID 25436638, 2014).
Bamforth-Lazarus syndrome (13 papers, 2011 to 2025). "In human subjects, homozygous loss-of-function mutations in the FOXE1 gene have been associated with severe hypoplasia or agenesis of the thyroid gland, as part of as the so-called Bamforth–Lazarus syndrome." (PMID 41303336, 2025). "Homozygous loss- and gain-of-function missense mutations in the forkhead domain of FOXE1 cause Bamforth–Lazarus syndrome, which is characterized by thyroid dysgenesis, cleft palate, spiky hair, as well as, in some cases, choanal atresia and bifid epiglottis." (PMID 36994096, 2023). "Very recently, a novel homozygous protein-truncating frameshift mutation in FOXE1 outside the FHD (Leu29Profs*75) was also reported to cause Bamforth–Lazarus syndrome." (PMID 36994096, 2023). "Most alleles conditioning the Bamforth-Lazarus syndrome are missense changes that impair the DNA-binding activity of the FOXE1 forkhead domain (amino acid positions 53 to 141)." (PMID 34070861, 2021). "FOXE1 dysfunction is associated with the formation of the cleft palate and dysgenesis of the thyroid gland in mouse models, but in humans homozygous FOXE1 mutations cause Bamforth–Lazarus syndrome characterized by cleft palate and congenital hypothyroidism." (PMID 33917041, 2021). "FOXE1 mutations in humans cause Bamforth-Lazarus syndrome, characterized by thyroid and craniofacial defects, although no reproductive tract abnormalities have been reported." (PMID 33008304, 2020). "Human FOXE1 mutations cause the Bamforth–Lazarus syndrome (OMIM 241850), which is associated with congenital hypothyroidism, cleft palate and spiky hair, with or without choanal atresia, bifid epiglottis and ocular hypertelorism." (PMID 23675434, 2013). "In humans, mutations of the gene encoding for thyroid transcription factor-2 (TTF-2 or FOXE1) result in Bamforth syndrome." (PMID 22304410, 2012). "Patients carrying homozygous mutations in FOXE1 present athyroidal hypothyroidism, spiky hair, choanal atresia, cleft palate and bifid epiglottis, known as Bamforth-Lazarus syndrome." (PMID 22177572, 2011). "Currently, eight pathogenic variants of FOXE1 have been associated with Bamforth–Lazarus syndrome." (PMID 41303336, 2025). "In humans, FOXE1 mutations cause the Bamforth–Lazarus syndrome (OMIM 241850)." (PMID 23675434, 2013). "Moreover, homozygous loss- and gain-of-function FOXE1 variants have both been implicated in Bamforth–Lazarus syndrome, characterised by congenital hypothyroidism, due to thyroid hypoplasia, ectopia or agenesis, cleft palate (CP), spiky hair with or without choanal atresia and bifid epiglottis." (PMID 38396644, 2024). "Based on the phenotypes in these individuals, features of the Bamforth–Lazarus syndrome were deemed more extensive, as the capacity of FOXE1 DNA binding decreased." (PMID 36994096, 2023). "Thus, c.9C>T appears to be a loss-of-function variant, similarly to others that have been described in the FOXE1 coding region, in patients with partial or complete Bamforth–Lazarus syndrome." (PMID 38396644, 2024). "It should be noted that we excluded NKX2-1 and FOXE-1 from our analysis, based upon the fact that the phenotype presenting in our cohort showed no signs of Bamforth-Lazarus syndrome or neurological findings." (PMID 30304112, 2018).
cleft palate (9 papers, 2017 to 2025). Cleft palate is a fissure type embryopathy that affects the soft and hard palate to varying degrees. "LHX8 and FOXE1 are transcription factors essential for craniofacial development and have been linked to cleft palate." (PMID 41075272, 2025). "FOXE1 gene expression previously has been described in the epithelium of the secondary palate which implies its regulatory purpose during palatogenesis process and the loss of FOXE1 function has been associated with formation of cleft palate and cleft lip in humans." (PMID 37733420, 2022). "This test indicated a statistically significant difference in the number of FOXE1 immunopositive connective tissue cells between the controls and the cleft palate tissue group (U=27.0, p=0.032)." (PMID 37733420, 2022). "Cleft lip with or without cleft palate and isolated cleft palate phenotypes have been associated with FOXE1 mutations." (PMID 33917041, 2021). "Median values of semiquantitative evaluation for BARX1, DLX4, FOXE1, HOXB3, and MSX2 immunoreactivity within the control tissue group, unilateral cleft lip tissue group, bilateral cleft lip tissue group, and cleft palate tissue group." (PMID 37733420, 2022). "Additionally, of note, both Subjects 7 and 11 had PDVs in genes included on the testing panel for cleft palate—GLI2 and FOXE1, respectively— and had craniofacial malformations involving the mouth." (PMID 33562221, 2021).
congenital hypothyroidism (9 papers, 2014 to 2023). A thyroid hormone deficiency present from birth. "FOXE1 is required for thyroid function and its homozygous mutations cause a rare syndromic form of congenital hypothyroidism (CH)." (PMID 37008944, 2023). "Altogether these data indicate that both the presence of 14 alanines and p.Leu107Val variant in the DBD may negatively affect FOXE1 expression patterns and functionality, further supporting their role in the development of congenital hypothyroidism." (PMID 37008944, 2023). "Loss of function mutations in TSHR, PAX8, NKX2.1, NKX2.5 and FOXE1 genes are responsible for some forms of inherited congenital hypothyroidism, with or without hypoplastic thyroid." (PMID 25146893, 2014).
orofacial cleft (9 papers, 2011 to 2025). A disorder of facial skeleton that is characterized by cleft lip and/or cleft palate that result in feeding, speech and hearing problems caused by failures during development. "DLX genes help to determine the patterning of the developing mandible and maxillary region in mammals while disruption of FOXE1 has been associated with the formation of different orofacial cleft types, including cleft lip." (PMID 37733420, 2022). "However, variants in the FOXE1 locus have also been shown to contribute significantly to non-syndromic orofacial clefts in multiple case-control and GWAS studies." (PMID 36994096, 2023). "FOXE1 has been previously associated with the formation of orofacial clefts." (PMID 33917041, 2021). "FOXE1 is responsible for palatogenesis, and it appears that casual mutations in noncoding regions that regulate FOXE1 expression are related to CL and CP, such as SNPs rs7850258, rs12342417, and rs10984103 within the FOXE1 locus that have been associated with high risk for orofacial clefting." (PMID 28928994, 2017). "For example, in individuals with nonsyndromic orofacial clefts, the major allele for common polymorphisms in IRF6 and FOXE1 are over-represented." (PMID 22140583, 2011). "How FOXE1 is involved in palate formation is largely unknown, and etiological mechanisms for FOXE1-related orofacial clefts remain therefore elusive." (PMID 36994096, 2023). "FOXE1 and EPHA3 are both orofacial clefting candidate genes and have not been associated previously with normal-range facial features." (PMID 33983923, 2021).
thyroid tumor (9 papers, 2009 to 2024). A benign or malignant neoplasm affecting the thyroid gland. "Forkhead factor E1 (FOXE1), also called TTF2 for thyroid transcription factor, was firstly isolated from cDNA of mouse and modified the development of the thyroid gland and their expression in thyroid tumors through encoding thyroid-specific transcription factors." (PMID 34950210, 2021). "Immunohistochemistry and RT-qPCR analyses of patients’ thyroid tumours revealed lower FOXE1 expression compared to adjacent normal and hyperplastic thyroid tissues." (PMID 38396644, 2024). "This opens an interesting future for understanding the role of FOXE1 in thyroid tumour cell migration and invasion." (PMID 19730683, 2009). "While FOXE1-specific studies are needed to further understanding the role of this gene in thyroid tumour cell migration and invasion, several studies have confirmed a tumoral role of forkhead family of transcriptional factors." (PMID 19730683, 2009). "To extend these observations to human tumors in general and in particular to thyroid tumors, we analyzed the pattern of FOXE1 expression in a range of tumor samples and normal tissues using data acquired from The Cancer Genome Atlas (TCGA) using the FireBrowse and Morpheus tools." (PMID 31846430, 2020). "Indeed, several studies reported a reduced TiTF1, PAX8 or FOXE1 expression in human thyroid tumors, especially in the poorly differentiated carcinomas." (PMID 22242190, 2012). "Our results revealed lower FOXE1 mRNA levels and absent protein expression in the patients’ thyroid tumours, when compared to matched adjacent normal and hyperplastic thyroid tissues, regardless of the FOXE1 mutation status, which is in agreement with data from The Cancer Genome Atlas (TCGA)." (PMID 38396644, 2024). "Furthermore, the expression of FOXE1 has been shown to be abnormal in thyroid tumors." (PMID 24489898, 2014). "However, we observed a clear correlation between FOXE1 expression and the differentiation state in PTC tumors, which is consistent with the data acquired in the thyroid tumor cells lines." (PMID 31846430, 2020). "Therefore, in the present study, we investigated both the expression and the promoter methylation status of the FOXE1 gene in a series of DTC tissues and thyroid tumor cell lines, and thyroid data from The Cancer Genome Atlas (TCGA) database, as well as their clinical relevance." (PMID 39588344, 2024). "Our previous findings about mRNA levels of thyroid specific transcription factors in thyroid tumours corroborate this hypothesis: both PAX8 and FOXE1 follow a similar expression pattern than DREAM, being highly expressed in benignant lesions compared to malignant lesions." (PMID 29641740, 2018).
breast carcinoma (5 papers, 2012 to 2024). "In breast cancer, hypermethylation was identified in the plasma of patients with a more aggressive disease (stage IV) and, in bladder cancer, FOXE1 methylation was suggested as one of the high-grade markers." (PMID 39588344, 2024). "FOXE1, as a tumor-specific methylation marker, can be detected in the pancreatic juice of pancreatic cancer patients and serum of breast cancer patients." (PMID 38734646, 2024).